GSTM1 (glutathione S-transferase mu 1)
Diseases named in the same sentence as GSTM1 in open-access papers (continued):
Sharing a sentence is not in itself a finding about the gene and the disease.
breast carcinoma (63 papers, 1999 to 2025). "In the study carried out on the Mexican population was found a relationship between the occurrence of the GSTM1 null genotype and the risk of breast cancer." (PMID 37819495, 2023). "A relationship between deletion in the GSTT1 and GSTM1 genes and an increased risk of many types of cancer occurrence (liver cancer, breast cancer, cervical cancer, head and neck cancer, oesophageal cancer, oral cancer, lung cancer) has been shown." (PMID 37819495, 2023). "Genetic mutations in GSTs, mainly the null genotype of GSTT1 and GSTM1 are considered a risk factor for breast cancer, but little is known about the presence of these polymorphisms and age at the diagnosis of breast cancer." (PMID 33513690, 2021). "The age at breast cancer diagnosis was correlated with the null polymorphism of GSTM1 and GSTT1, both alone or in association." (PMID 33513690, 2021). "As well, age at breast cancer diagnosis was correlated with GSTM1 and GSTT1 genotypes, together with other polymorphisms in the estrogen metabolic pathway, namely with CYP1B1 Val432Leu and MTHFR C677T polymorphisms." (PMID 33513690, 2021). "Pooled estimates of association of GSTM1 polymorphism and breast cancer risk, only studies with high quality, matching, and genotyping examination done bindly or quality control." (PMID 32155154, 2020). "It was also demonstrated that risk for breast cancer was increased in passive smokers carrying the GSTM1 null (OR=2.56; 95% CI=1.38-4.75) or GSTT1 positive (OR=2.00; 95% CI=1.05-3.83) genotypes." (PMID 30803216, 2019). "Passive smoking appears to increase the risk of developing breast cancer among Filipinos carrying the GSTM1 null and GSTT1 positive genotypes." (PMID 30803216, 2019). "There was no clear difference in the association between acrylamide intake and ER+ breast cancer risk between the genotypes of GSTM1." (PMID 29445914, 2019). "Our study suggests that the GSTM1 polymorphism plays a complex role in influencing the chemotherapy response and breast cancer survival." (PMID 30032483, 2018). "Our study was to evaluate the association between GSTM1 null/present polymorphism and chemotherapy treatment outcome in breast cancer patients." (PMID 30032483, 2018). "We report a common CNV approximately 3 kb in size in a locus encompassing GSTM1 associated with breast cancer risk." (PMID 29116104, 2017). "We have identified a CNV (Chr1:110230244-110233070) showing association with breast cancer and harbouring the GSTM1 gene." (PMID 29116104, 2017). "The results of this study indicated a U-shaped association of GSTM1 with breast cancer, which challenges the linear gene-dosage effect of GSTM1 that was previously proposed." (PMID 28747156, 2017). "The top candidate was a SNP in the promoter of GSTM1 whose expression is associated with survival in breast cancer patients." (PMID 27964748, 2016). "Several studies have addressed the role of GSTT1 and GSTM1 gene deletions as risk factors in breast carcinoma, but the results are conflicting." (PMID 14562023, 2003). "The authors designed a large study to investigate the susceptibility and prognostic implications of the GSTT1 and GSTM1 gene deletions in breast carcinoma." (PMID 14562023, 2003). "Our data provide evidence against a substantially increased risk of breast carcinoma associated with GSTM1 homozygous gene deletion." (PMID 14562023, 2003). "In this study, we determined GSTM1 polymorphisms in a population of 437 female controls from the west of France and 361 community breast cancer patients." (PMID 9888479, 1999). "The influence of polymorphisms of the glutathione S-transferase gene GSTM1 in breast cancer susceptibility has been assessed in this study." (PMID 9888479, 1999).
breast carcinoma (continued). "In this regard, the present study was designed to investigate the impact of mutations acquisition in low penetrance genes during the lifetime in breast cancer development—more specifically, the impact of the null polymorphisms in GSTM1 and GSTT1 in breast cancer development at later ages." (PMID 33513690, 2021). "Meta-analysis of the association of GSTM1 polymorphism with risk of breast cancer." (PMID 32155154, 2020). "Besides, it seems that GSTM1 distinctly involves the susceptibility to cancer including breast cancer due to its possible distinctive substrate qualities." (PMID 32334487, 2020). "Here we hypothesize that GSTM1‐null/present polymorphism may have an influence on breast cancer progression and chemotherapy treatment response." (PMID 30032483, 2018). "The interaction between GSTM1‐null/present polymorphism and adjuvant chemotherapy may lead to potential drug resistance and influence the survival of breast cancer patients." (PMID 30032483, 2018). "In this study, we evaluated the role of GSTM1‐null/present polymorphism in the treatment outcome of patients with breast cancer, and we also investigated whether this effect would be influenced by adjuvant chemotherapy or not." (PMID 30032483, 2018). "Risk of FAC-related anemia of any grade was elevated by polymorphic allele C of p.Asn118= (rs11615) variant in ERCC1 gene, common homozygote GG of ABCC2 p.Val417Ile (rs2273697) polymorphism, presence of both GSTT1 and GSTM1 genes and triple-negativity of breast cancer." (PMID 29507678, 2018). "Several studies have shown coding and non-coding polymorphisms in GSTM1 could modify the risk for breast cancer suggesting the importance of this gene in this disease." (PMID 27964748, 2016). "However, smokers carrying the GSTM1 null genotype were at significantly elevated risk for breast cancer overall in a meta-analysis of seven studies." (PMID 21080951, 2010). "In this regard, Parl (2005) found an increased risk of breast cancer among GSTM1 positive women, and suggested that the combination of all GST conjugation activities may cause glutathione depletion and therefore result counterproductive." (PMID 21572833, 2008). "The complete gene deletion of GSTM1 and the (GG) genotype of GSTP1 polymorphism (rs1695) have shown significant associations with breast cancer in South Indian74 and Jordanian women." (PMID 40290119, 2025). "The risk association between GSTM1/GSTT1 deletions and breast cancer development/prognosis has been consistently reported across various studies in Americans, Europeans, and Asians." (PMID 40290119, 2025). "In cancer patients, SFN showed promise in early-stage prostate and breast cancer, particularly in GSTM1-positive individuals, but had limited effects in advanced cases." (PMID 40988712, 2025). "In another meta-analysis, it was also shown the association between the GSTM1 and GSTP1 gene polymorphisms and an increased risk of breast cancer occurrence in the Asian population (especially in East Asia)." (PMID 37819495, 2023). "In other study have also shown that the rs1695 polymorphism in the GSTP1 gene, the GSTM1 null genotype and the GSTT1 null genotype were also associated with an increased incidence of breast cancer." (PMID 37819495, 2023). "In previous studies, many researchers found that age was significantly correlated with GSTM1/2 in multiple diseases, including cataract, macular degeneration, essential hypertension, breast cancer, Parkinson’s disease, and ovarian damage." (PMID 35965498, 2022).
breast carcinoma (continued). "GSTM1 was reported to be a predictive biomarker for the efficacy of chemotherapy in breast cancer and ovarian cancer." (PMID 33931597, 2021). "A two-way combination of GSTT1 and GSTM1 genotypes with the age of the patients at breast cancer diagnosis was also performed." (PMID 33513690, 2021). "Regarding MCF10DCIS.com, we observed lower expression of the proliferation markers, when compared to the breast cancer cell lines, and low GSTM1 and PGR expression." (PMID 34238275, 2021). "Pooled estimates of association of the combined effects of GSTM1 present/null and GSTT1 present/null and breast cancer risk, only studies with high quality, matching, and genotyping examination done bindly or quality control." (PMID 32155154, 2020). "This research aims to explore the frequency and role of GSTM1 and GSTT1 polymorphisms on survival among Thai patients with breast cancer." (PMID 32856852, 2020). "For genes coding for phase II xenobiotics metabolizing enzymes, the deletion of GSTT1 and GSTM1 were reported by Khedhaier to predict the early onset and prognosis of breast cancer among Tunisian women." (PMID 33659210, 2020). "False-positive report probability values for the previous meta-analyses on GSTM1, GSTT1, and GSTP1 IIe105Val polymorphisms with breast cancer risk." (PMID 32155154, 2020). "A total of fourteen previous meta-analyses between 2004 and 2016 have been published to analyze the individual GSTM1 present/null, GSTT1 present/null, and/or GSTP1 IIe105Val polymorphisms on breast cancer (BC) risk." (PMID 32155154, 2020). "The deletion polymorphisms of GSTM1 and GSTT1 genes are associated with reduced enzyme activity that influenced clinical outcomes of chemotherapeutic agents in breast cancer." (PMID 32856852, 2020). "Meta-analysis of the combined effects of GSTM1 present/null and GSTT1 present/null on breast cancer risk." (PMID 32155154, 2020). "In conclusion, this study is the first study to explore the role of GSTM1 and GSTT1 polymorphisms with survival in breast cancer patients in Thailand." (PMID 32856852, 2020). "In this study, 198 breast cancer patients were genotyped, and the result showed that among Thai breast cancer patients, the frequency of the GSTM1 and GSTT1 null genotype was 65.70% and 33.30%, respectively." (PMID 32856852, 2020). "Pooled estimates of association of the combined effects of GSTM1 present/null and GSTP1 IIe105Val and breast cancer risk, only studies with high quality, matching, HWE, and genotyping examination done bindly or quality control." (PMID 32155154, 2020). "Meta-analysis of the combined effects of GSTM1 present/null, GSTT1 present/null and GSTP1 present/null on breast cancer risk." (PMID 32155154, 2020). "Meta-analysis of the combined effects of GSTM1 present/null and GSTP1 IIe105Val on breast cancer risk." (PMID 32155154, 2020). "Fourteen previous meta-analyses have been published to analyze the polymorphisms of individual GSTM1 present/null, GSTT1 present/null, and GSTP1 IIe105Val on breast cancer (BC) risk." (PMID 32155154, 2020). "Meta-analyses have shown the association of polymorphisms in GSTM1 and GSTT1 with increased breast cancer risk in Asians, most notably in Chinese populations." (PMID 30803216, 2019). "Breast cancer associated CNVs overlapping with the genes APOBEC3B, GSTM1 and FGFR2 were validated using the TaqMan assay." (PMID 29116104, 2017). "Polymorphisms in GSTM1, GSTP1, and GSTO1 enzymes increase the risk of developing breast cancer and hepatocellular carcinoma." (PMID 26682223, 2015). "For example, polymorphisms in the GSTM1 and GSTP1 genes increase the risk of developing breast cancer and hepatocellular carcinoma." (PMID 26682223, 2015). "Using functional genomics we detected the overexpression of GSTM1 and GSTM4 in methotrexate-resistant MCF7 breast cancer cells, and determined that methotrexate was susceptible of glutathionylation by GSTs." (PMID 23675469, 2013).
breast carcinoma (continued). "It has been reported that the deletion of the GSTM1 and GSTT1 gene as well as the variant allele of the GSTP1 rs1695 polymorphism impact overall breast cancer risk." (PMID 23226154, 2012). "Only one breast cancer study has reported on a potential interaction between GSTM1 null genotype and PAH–DNA adducts." (PMID 19440493, 2009). "For example, for the GSTM1-CYP2e1 locus pair at 1 KBP in the second breast cancer study, the common over-represented keywords for the MeSH vocabulary are: "cyp2e1", "ethanol", "smoke", "area", "stomach"', "toxicity", and "xenobiotics"." (PMID 19208188, 2009). "We estimated the breast cancer risk associated with multiple polymorphisms in the GST gene (GSTA1, GSTM1, GSTP1, and GSTT1) and the interaction with PAH–DNA adducts and cigarette smoking." (PMID 19440493, 2009). "Combined effect of all three GSTT1, GSTM1, and GSTP1 variants have been reported to have greater than a 3-fold increase in breast cancer risk compared with women with the common genotype for all three polymorphisms." (PMID 19440493, 2009). "We found little statistical evidence that PAHs interacted with GSTT1, GSTM1, GSTP1, and GSTA1 polymorphisms to further increase breast cancer risk." (PMID 19440493, 2009). "Several studies highlighted the role of XME gene polymorphisms such as CYP1A1, CYP1B1, CYP2D6, mEH, GSTT1, GSTM1 and NAT1 in treatment efficacy as well as survival after treatment of breast carcinoma." (PMID 18423013, 2008). "SNP-SNP interactions in breast cancer development have been also reported in other studies, which targeted the SNPs of the carcinogen metabolism genes, including GSTM1, GSTT1, GSTP1, GSTM3 and CYPs." (PMID 16672066, 2006). "In this case–control study, we sought to determine if the polymorphisms of GSTM1 and GSTT1 modify the relationship between alcohol drinking and breast cancer risk based on detailed information on lifetime alcohol consumption." (PMID 12556960, 2003). "We analysed the relationship between gene deletion of GSTM1 and GSTT1 and the susceptibility to breast carcinoma in this population." (PMID 14562023, 2003). "The authors used the polymerase chain reaction to characterise the variation of the GSTT1 and GSTM1 genes in 309 unrelated Tunisian patients with breast carcinoma and 242 healthy control subjects." (PMID 14562023, 2003). "The deletion polymorphisms of GSTM1 and GSTT1 genes are associated with reduced enzyme activity that could be associated with the susceptibility to breast cancer and treatment outcome." (PMID 32856852, 2020). "GSTM1 and GSTT1 null polymorphisms are associated with risk factors causing the Asian breast cancer and also GSTP1 Val105Ile (rs1695) polymorphism is a risk factor for Caucasians breast cancer." (PMID 33083304, 2020). "The GSTM1 null and GSTT1 null appear to be associated with a significant risk of several types of cancers, such as hematological neoplasm and breast cancer." (PMID 32102530, 2020). "Because of the limited information regarding GSTM1 and GSTT1 polymorphisms among Thai patients with breast cancer, therefore, the objective of this research is to explore the frequency and association between these two genetic polymorphisms on survival in Thai patients with breast cancer." (PMID 32856852, 2020). "Postmenopausal women with GST polymorphisms leading to low or no GSTT1, GSTP1 and GSTM1 activity benefitted to a greater extent from the consumption of marine ω3 fatty acids in the context of breast cancer." (PMID 31505792, 2019). "Hence, this study analyzed the association of polymorphisms in the GSTM1 and GSTT1 genes in a set of Filipino breast cancer cases and matched clinically healthy controls." (PMID 30803216, 2019). "The lack of association of GSTM1 null genotype with breast cancer has also been seen in Iranian, Lebanese, Pakistani, Taiwanese, Icelandic, Mexican, and Caucasian and African-American populations." (PMID 30803216, 2019).
breast carcinoma (continued). "It is suggested that the GSTM1‐present genotype might prevent progression in breast cancer patients." (PMID 30032483, 2018). "In summary, our results suggest that breast cancer patients with GSTM1‐present genotype may gain a better survival outcome when comparing to their wild‐type counterparts, but the benefit probably compromises due to the intervention of adjuvant chemotherapy." (PMID 30032483, 2018). "Therefore, we aimed to investigate possible associations between germline genetic polymorphisms within GSTM1, GSTT1, GSTP1, SULT1A1 and UGT1A1 genes and breast cancer clinicopathological characteristics together with disease progression." (PMID 25648141, 2015). "Neither GSTM1 nor GSTT1 null mutations were associated with breast cancer-specific or all-cause mortality." (PMID 24083102, 2013). "Our results from stepwise regression showed a non-significant effect modification by GSTM1, with higher risk of breast cancer associated with smoking among those with the GSTM1 null genotype." (PMID 21080951, 2010). "The present population-based case-control study of breast cancer in Germany evaluated the role of genetic polymorphisms in Phase I and II enzymes NAT1 and NAT2 in the AA pathway and CYP1A1, CYP1B1, GSTM1 and GSTT1 in the PAH pathway and cigarette smoke exposure in breast carcinogenesis." (PMID 21080951, 2010). "Another study in Taiwan reported that the combination of CYP2E1 and GSTM1 was associated with breast cancer without the habits of cigarette smoking and alcohol consumption." (PMID 17603900, 2007). "Neither of the GSTM1 allelotypes were significantly associated with breast cancer risk for all women combined or among pre- or postmenopausal women (data not shown)." (PMID 12556960, 2003). "No direct correlation was found between polymorphism in the GSTM1 gene and the breast carcinoma onset in Tunisians." (PMID 14562023, 2003). "To determine if breast cancer risk is associated with GSTM1 and GSTT1 genetic polymorphisms, and to evaluate the effect modification between GST genotypes and alcohol consumption in the risk of breast cancer, we conducted a case–control study in the state of Connecticut in the period 1998 and 2001." (PMID 12556960, 2003). "Our results suggest that the GSTM1 null genotype may play a role in post-menopausal breast cancer development." (PMID 9888479, 1999). "Another analysis conducted on the Filipino population have found that GSTM1 and GSTT1 null genotypes can be to recognise as a risk factors for development of breast cancer, but this risk may increase when these genotypes are combined with lifestyle or environmental factors." (PMID 37819495, 2023). "Among the polymorphisms studied in GSTs, Glutathione S-transferase Theta1 (GSTT1) and Glutathione S-transferase Mu1 (GSTM1) null polymorphisms, the homozygous genotype of which implies the total absence of the enzyme, has previously been related to breast cancer risk by our research team." (PMID 33513690, 2021). "Moreover, each gene expresses an increased risk genotype (GSTM1 null, GSTT1 null and GSTP1 Val/Val), which may be involved in breast cancer susceptibility when more than one are expressed in each individual." (PMID 32155154, 2020). "Thus, this study aimed to determine whether polymorphisms in the GSTM1 and GSTT1 genes are associated with breast cancer among selected Filipinos." (PMID 30803216, 2019). "SNP based studies in the GSTM1 gene SNPs associated with breast cancer risk but not with prognosis." (PMID 29116104, 2017). "In addition, the GSTM1 and GSTT1 deletion as well as the GSTP1 rs1138272 variant, were suggested to affect tobacco smoke-related breast cancer risk pointing to the potentially critical role of GSTs in the elimination of exogenous carcinogenic compounds such as polycyclic aromatic hydrocarbons." (PMID 23226154, 2012). "The GSTM1 null genotype has not been found to confer susceptibility to breast cancer." (PMID 21080951, 2010).